IL20 (interleukin 20)
Diseases named in the same sentence as IL20 in open-access papers (continued):
Sharing a sentence is not in itself a finding about the gene and the disease.
prostate carcinoma (5 papers, 2015 to 2021). A carcinoma that arises from epithelial cells of the prostate gland. "In vivo, anti-IL-20 mAb 7E not only shrank the tumor mass but also prevented prostate cancer-induced bone loss." (PMID 29690863, 2018). "The present study provides evidence that IL–20 is associated with the pathogenesis of prostate cancer." (PMID 26440411, 2015). "Inhibition of the pro-inflammatory interleukin-20 (IL-20) suppresses prostate cancer-induced osteolysis in a xenograft mouse model, at least in part, via the AKT pathway." (PMID 34064589, 2021). "In vitro, IL-20 significantly enhances the proliferation, migration, and anchor-independent growth in prostate cancer cells." (PMID 29690863, 2018). "In PC-3 prostate cancer-induced osteolytic bone metastasis model, we found the similar effects, treatment of anti-IL-20 mAb 7E not only restrained prostate cancer growth but also protected against cancer-induced osteolysis." (PMID 29690863, 2018). "IL-20 and its three receptors transcripts are detected in the human prostate adenocarcinoma tissue samples, indicating that prostate cancer is one of the targets of IL-20." (PMID 29690863, 2018). "In the present study, we found that IL–20 directly induced the cleavage of RANKL from the surface membrane of prostate cancer cells by upregulating cathepsin G expression." (PMID 26440411, 2015). "IL–20 and its receptors were all expressed in prostate tumor tissue specimens and prostate cancer cell lines (PC–3 and LNCaP)." (PMID 26440411, 2015). "Immunohistochemical staining showed that IL–20 and its receptors were expressed in human PC–3 and LNCaP prostate cancer cell lines and in prostate tumor tissue from 40 patients." (PMID 26440411, 2015). "We conclude that IL–20 is involved in the cell migration, colony formation, and tumor-induced osteolysis of prostate cancer." (PMID 26440411, 2015). "In conclusion, our study demonstrates that IL–20 has an autocrine effect and provides a microenvironment that affects tumor progression and prostate cancer-induced osteolysis." (PMID 26440411, 2015). "Based on our in vitro data, we speculated that IL–20 might promote osteoclastogenesis by regulating sRANKL and cathepsin G expression in prostate cancer cells." (PMID 26440411, 2015). "We show that IL–20 is a local mediator in the microenvironment that affects prostate cancer cells." (PMID 26440411, 2015). "IL–20 and its three receptors were expressed in our clinical specimens and in the PC–3 and LNCaP prostate cancer cell lines, which suggested both autocrine and paracrine effects of IL–20 on prostate tumors and contributions to the pathogenesis of prostate cancer." (PMID 26440411, 2015). "To investigate whether prostate cancer cell is the target cell for IL–20, we used IHC staining to analyze the expression levels of IL–20’s receptors (IL-20R1, IL-20R2, and IL-22R1) in prostate adenocarcinoma tissue samples from 40 patients." (PMID 26440411, 2015). "To clarify the role of IL–20 in the pathogenesis of prostate cancer, we first examined whether IL–20 and its receptors (IL-20R1, IL-20R2, and IL-22R1) were expressed in prostate cancer cell lines." (PMID 26440411, 2015). "IL–20 affected prostate cancer cell migration and colony formation, and promoted tumor progression." (PMID 26440411, 2015). "Therefore, we investigated the expression of IL–20 and its biological function in prostate cancer cells and assessed the therapeutic potential of 7E in xenograft prostate cancer mouse models." (PMID 26440411, 2015). "Antagonizing IL–20 might have therapeutic potential in prostate cancer." (PMID 26440411, 2015). "Thus, we hypothesize that IL–20 produced by prostate cancer cells is important for inducing EMT in the primary tumor and then for promoting tumor cell migration and local invasion." (PMID 26440411, 2015).
prostate carcinoma (continued). "In the present study, we found that IL–20 regulated EMT-associated markers (E-cadherin, N-cadherin, vimentin, and fibronectin), affected prostate cell migration, and increased anchorage-independent growth in prostate cancer by inducing the phosphorylation of p38, ERK1/2, AKT, and NF-κB signals." (PMID 26440411, 2015). "We hypothesize that IL–20 promotes the growth of prostate cancer cells." (PMID 26440411, 2015). "However, little is known about the role of IL–20 in prostate cancer." (PMID 26440411, 2015). "Therefore, we wondered whether inhibiting IL–20 would reduce prostate cancer-induced osteolysis in vivo." (PMID 26440411, 2015). "We also found that IL-20 enhances RANKL production through regulating cathepsin G and cathepsin K in prostate cancer cells." (PMID 29690863, 2018). "In vitro, IL–20 upregulated N-cadherin, STAT3, vimentin, fibronectin, RANKL, cathepsin G, and cathepsin K, and increased the migration and colony formation of prostate cancer cells via activated p38, ERK1/2, AKT, and NF-κB signals in PC–3 cells." (PMID 26440411, 2015). "Therefore, IL–20 might be a novel target for treating prostate cancer." (PMID 26440411, 2015).
atopic dermatitis (4 papers, 2017 to 2025). "For example SDC-4 (syndecan-4) mRNA levels were increased in atopic dermatitis compared with normal skin samples and the inflammatory mediators IL-17, IL-20, IL-24, IL-31, and IL-33 were also elevated in atopic dermatitis." (PMID 29383128, 2017).
COVID-19 (4 papers, 2021 to 2024). A disease caused by infection with severe acute respiratory syndrome coronavirus 2. "We also report that the cytokine response was more diverse in COVID-19 patients, which is highlighted by IL-2, IL-4, and IL-20 signaling, while HIV-1+ individuals primarily exhibited high levels of NF-kB signaling." (PMID 36992700, 2023). "PLWH with COVID-19 with a detectable VL had significantly lower concentrations of IL-2, IL-4, IFN-γ, IL-20, IL-22, IL-35, and IL-12p40 than PLWH with COVID-19 with an undetectable VL." (PMID 39597537, 2024). "Enrichment of IL-20, IL-2, IL-6, KIT, and JAK-STAT signaling pathways was unique to monocytes and DCs from patients with COVID-19, suggesting that innate immune cells may be much more active and cytotoxic in COVID-19 compared to in HIV-1." (PMID 36992700, 2023). "We found that acute COVID-19 neutrophils secreted reduced G-CSF, MIP-1α, MIP-1β, MCP-1, IL-2, SDF-1α, IL-9, IL-17A, IL-18, IL-20 and IL-23 levels, but secreted increased soluble PD1, IP-10 and MIP-2α levels compared to rec-phase and healthy neutrophils upon bacterial challenge." (PMID 35007290, 2022).
hepatocellular carcinoma (4 papers, 2017 to 2025). A malignant tumor that arises from hepatocytes. "Additionally, IL-20 is associated with muscle-invasive bladder cancer, while hepatocellular carcinoma (HCC) tumor tissue expressed higher levels of IL-20 than did non-tumor tissue." (PMID 40806452, 2025). "In liver biopsies from patients with fibrosis, cirrhosis, and hepatocellular carcinoma, IL-20 levels were significantly elevated in hepatocytes and hepatic stellate cells compared to normal liver tissue from healthy individuals." (PMID 37762066, 2023). "Both IL-20 and cyclin D1 mRNA were expressed in three different human hepatoma cell lines." (PMID 29242565, 2017). "However, the role of IL-20 in hepatocellular carcinoma (HCC) is unclear." (PMID 29242565, 2017).
osteoarthritis (4 papers, 2015 to 2021). A noninflammatory degenerative joint disease occurring chiefly in older persons, characterized by degeneration of the articular cartilage, hypertrophy of bone at the margins and changes in the synovial membrane. "IL-20 levels in SF were significantly higher (p < 0.001) in RA patients (60 pg/ml, 24–445 pg/ml) than in patients with osteoarthritis (OA) (32 pg/ml, 11–55 pg/ml)." (PMID 26268325, 2015).
acute kidney injury (3 papers, 2012 to 2020). Sudden and sustained deterioration of the kidney function characterized by decreased glomerular filtration rate, increased serum creatinine or oliguria. "Previous studies indicated that IL-20 and its receptors are increased in the kidneys of mice with acute renal failure (ARF), which might cause apoptosis and necrosis in tubular epithelial cells by activating caspase-9." (PMID 32028746, 2020). "The mRNA expression of Il19, Il20 and Il24 increased in the kidney of rats with I/R-induced acute kidney injury and in the kidney of diabetic rats as well." (PMID 32306980, 2020). "We also demonstrated the increased renal expression of Il19, Il20, and Il24 in an I/R-induced rat model of acute renal failure and in the STZ-induced rat model of diabetic nephropathy, as well." (PMID 32306980, 2020).
Autoimmunity (3 papers, 2021 to 2025). The occurrence of an immune reaction against the organism's own cells or tissues. "Understanding the intricate interplay of cytokines, such as IL-19, IL-20, and IL-24, with their receptors and their influence on autoimmunity can offer valuable insights into the therapeutic potential of Tai Chi exercise." (PMID 41551693, 2025). "Although signaling of subfamily IL-20 is well documented for many inflammatory and autoimmune disorders, its contribution to the pathogenesis of neuroinflammatory disorders has not been reported." (PMID 34557075, 2021).
colon cancer (3 papers, 2016 to 2021). "Recently IL-20 has been shown to have roles in breast and colon cancers." (PMID 27806114, 2016). "This study evaluated the effects of IL-20, IL-22, and IL-24 in epithelial renewal using the LS174T human colon cancer epithelial cell line." (PMID 31311100, 2019).
dermatitis (3 papers, 2021 to 2022). An inflammatory process affecting the skin. "In this study, immunofluorescence and qPCR analysis showed that MLT significantly reduced the infiltration of CD4+ T cells in rosacea-like dermatitis and suppressed the expression of Th1-related genes (IFN-γ, CCR5, CXCL9, CXCL10) and Th17-related genes (STAT3 and IL-20) in rosacea-like dermatitis." (PMID 34899707, 2021).
gastric cancer (3 papers, 2018 to 2021). A primary or metastatic malignant neoplasm involving the stomach. "The IL-20 cytokine IL-24 can induce apoptosis in gastric cancer cells and inhibits tumor angiogenesis in vivo in a chicken embryonic allantois model." (PMID 29967613, 2018). "A function of IL-19 and IL-20 in the development of gastric cancer is not reported in the literature so far." (PMID 29967613, 2018). "Taken together, this indicates that the relevance of IL-20 cytokines for the development of gastric cancer is not well understood and that members of the IL-20 cytokine family may promote or protect from gastric cancer." (PMID 29967613, 2018).
glioblastoma (3 papers, 2012 to 2020). The most malignant astrocytic tumor (WHO grade IV). "We previously reported that IL-1β expression was upregulated by IL-20 in glioblastoma cells and oral cancer cells." (PMID 32929072, 2020). "Hypoxia has been shown to induce the expression of IL-20 mRNA and protein by glioblastoma cells, while mixed primary glia show a rapid (within 2 h) and transient expression of mRNA encoding IL-20 following challenge with bacterial LPS." (PMID 30542269, 2018). "Similarly, glioblastoma cells exposed to IL-20 demonstrate phosphorylation of STAT3, ERK and Akt." (PMID 30542269, 2018). "Within the CNS, inhibition of IL-20 using a neutralizing antibody has been shown to limit the inflammatory damage associated with acute ischemic brain injury, and IL-20 exposure has been demonstrated to promote the release of the potent chemoattractants MCP-1 and IL-8 by a glioblastoma cell line." (PMID 30542269, 2018). "IL-20 treatment also induced the activation of Jak2/Stat3 and ERK1/2 pathway in GBM8901 glioblastoma cells." (PMID 22962576, 2012).
inflammatory bowel disease (3 papers, 2016 to 2020). A spectrum of small and large bowel inflammatory diseases of unknown etiology. "Furthermore, levels of IL-19, IL-20, IL-24 and IL-26 are also elevated in serum of patients with inflammatory bowel disease, which is associated with the intergenic 6q23 variants tagged by rs6920220." (PMID 27799070, 2016). "Recently, increased expression of IL-19, IL-20 and IL-24 has been demonstrated in the colonic mucosa and also in peripheral blood mononuclear cells (PBMCs) of patients with inflammatory bowel diseases (IBD)." (PMID 31973719, 2020).
Liver Disease (3 papers, 2018 to 2024). "In conclusion, IL-20 is closely associated with liver diseases and has significant potential for the treatment of liver diseases." (PMID 38699038, 2024). "Similar to liver diseases, IL-20 behaves as a pro-inflammatory cytokine in most diseases and is involved in disease progression." (PMID 38699038, 2024). "Nanovector systems targeting IL-20 offer new possibilities for the treatment and prevention of liver diseases." (PMID 38699038, 2024). "The regulatory mechanism of IL-20 in liver disease is mediated by two main components: receptors and signaling pathways." (PMID 38699038, 2024). "As more works are conducted in the near future, we expect to obtain more evidence to justify the treatment of anti-IL-20 mAb in liver disease." (PMID 38699038, 2024). "To better understand the crucial roles and connections between IL-20 expression and the emergence of liver disorders, we will briefly review the biological regulatory roles of IL-20 in various liver diseases." (PMID 38699038, 2024). "Mouse models have long been said to be instructive in the clinical application of disease, and IL-20-deficient mice are frequently used to illustrate the pro-inflammatory role of IL-20 in liver disease." (PMID 38699038, 2024). "As the mechanism of action of IL-20 continues to be elucidated, it is expected to be applied as a therapeutic target for the treatment of liver diseases." (PMID 38699038, 2024). "Thus, inhibiting IL-20 expression not only by antagonizing itself or its receptor, but also by using exogenous drugs such as hormones in combination, opens new avenues for the treatment of IL-20 in liver disease." (PMID 38699038, 2024). "To demonstrate the therapeutic potential of IL-20, we enumerated the current clinical studies related to IL-20 to understand the functions of IL-20 in different diseases and to establish a foundation for developing the potential functions of IL-20 in liver diseases." (PMID 38699038, 2024). "In this review, we summarize the main molecular features and biological functions of IL-20 and highlight the specific regulatory mechanisms and clinical applications that provide a basis for understanding the relationship between IL-20 and various types of liver disease." (PMID 38699038, 2024). "This review highlights the potential of targeting IL-20 in liver diseases, elucidates the potential mechanisms of IL-20 inducing liver injury, and suggests multiple viable strategies to mitigate the pro-inflammatory response to IL-20." (PMID 38699038, 2024). "Insights into IL-20 in specific tissue and disease contexts may help develop new strategies for the treatment of liver diseases." (PMID 38699038, 2024). "Genomic CRISPR/Cas9-based screens may be a feasible way to further explore the signaling pathways and regulation of IL-20 in liver diseases." (PMID 38699038, 2024). "Interestingly, Chiu and coworkers, evaluated the role of IL-20 in liver disease by several approaches, liver biopsies of 66 patients with several liver diseases compared to 3 healthy subjects, a mouse model with liver injury and in vitro experiments with a rat hepatocyte Clone-9 cells." (PMID 36211332, 2022). "Unfortunately, the precise mechanism of IL-20 and STAT5 in liver diseases has not been definitively elucidated." (PMID 38699038, 2024).
pancreatic cancer (3 papers, 2020 to 2023). "IL-20 induced M2 macrophage differentiation from bone marrow-derived macrophages in vitro, and IL-20 blockade reduced CD206+ (marker for M2) macrophages in a pancreatic cancer model in vivo." (PMID 34359625, 2021). "A methyl thiazol tetrazolium (MTT) assay showed that an anti-IL-20 mAb (7E) suppressed IL-20-mediated cell proliferation in these three pancreatic cancer cell lines, suggesting that IL-20 is pivotal in pancreatic cancer cell proliferation." (PMID 32929072, 2020). "IHC staining confirmed the upregulation of IL-20 expression in pancreatic tumor tissue samples from KPC mice compared with pancreatic tissue samples from wild-type (WT) mice." (PMID 32929072, 2020). "We determined the pathogenic role of IL-20 in vivo by using Pdx-1-Cre (KPC) mice, which spontaneously develop pancreatic tumors that mimic the progression of PDAC in humans." (PMID 32929072, 2020). "To investigate whether blockade of IL-20 affects macrophages in pancreatic tumors, we stained tumor tissue samples for a macrophage marker (F4/80) and an M2-type macrophage marker (CD206)." (PMID 32929072, 2020). "Pancreatic tumors from the orthotopic model showed colocalization of IL-20 and PD-L1 in vivo, which indicated that IL-20 might be involved in PD-L1 regulation." (PMID 32929072, 2020). "We next investigated whether IL-20 blockade by 7E inhibits orthotopic pancreatic tumor growth." (PMID 32929072, 2020). "Human and mouse pancreatic cancer cell lines (PANC-1, BxPC-3, and PANC-02) expressed endogenous IL-20 and its receptors, and 7E inhibited the proliferation of these cell lines in vitro." (PMID 32929072, 2020). "Immunostaining showed that both human and murine pancreatic cancer cell lines (PANC-1, BxPC-3, and PANC-02) expressed IL-20 and its receptors." (PMID 32929072, 2020).
anemia (2 papers, 2022 to 2023). A reduction in the number of red blood cells, the amount of hemoglobin, and/or the volume of packed red blood cells. "Another 5 markers were only related to clinical disease severity and anemia including sCD30, IL-8, IL-20, IL-29/IFNδ1 and TNF-α." (PMID 38162636, 2023). "Luminex assay results for IL-19, IL-20, IL-26, IL-28A and IL-29 levels in sera of HC, Healthy controls; IDA, Iron deficiency anemia patients; PA, Pernicious anemia patients." (PMID 35479078, 2022). "We investigated the serum levels of different cytokines, such as IL-19, IL-20, IL-26, IL-28A and IL-29 in patients with pernicious anemia and autoimmune gastritis or iron deficient anemia without autoimmune gastritis." (PMID 35479078, 2022).
bone fracture (2 papers, 2016 to 2018). "To clarify the in vivo role of IL-20 in osteoblast differentiation, we generated a mouse model of bone fracture to analyze whether IL-20 is associated with bone fractures." (PMID 27075747, 2016). "To confirm the clinical correlation between IL-20 and sclerostin in patients with bone fracture, we collected their serum and used ELISA to analyze their IL-20 and sclerostin." (PMID 27075747, 2016). "Our results demonstrated that IL-20 is involved in osteoregulation and anti-IL-20 mAb is a potential therapeutic for treating bone fracture or metabolic bone diseases." (PMID 27075747, 2016). "Although serum IL-20 level was upregulated in both IL-20R1+/+ and IL-20R1−/− mice after bone fracture, we found that IL-20 level was significantly higher in IL-20R1+/+ mice than in IL-20R1−/− mice between 5 and 21 days post-fracture." (PMID 27075747, 2016). "Also, we found the IL-20 is upregulated in the serum of bone fracture animal model, and anti-IL-20 mAb 7E treatment enhanced bone formation." (PMID 29690863, 2018). "Serum IL-20 was significantly correlated with serum sclerostin in patients with bone fracture." (PMID 27075747, 2016). "Therefore, we explored whether IL-20 regulates osteoblast differentiation and assessed the effects of IL-20 blockade in bone fracture mouse model." (PMID 27075747, 2016). "Linear regression analysis showed that IL-20 was not correlated with sclerostin in healthy volunteers (r = 0.054), but positively correlated with sclerostin in patients with bone fracture (r = 0.807)." (PMID 27075747, 2016).